MAPK4 (mitogen-activated protein kinase 4)
Diseases named in the same sentence as MAPK4 in open-access papers (continued):
Sharing a sentence is not in itself a finding about the gene and the disease.
cancer (35 papers, 2014 to 2025). A tumor composed of atypical neoplastic, often pleomorphic cells that invade other tissues. "As one of the mitogen-activated protein kinases, MAPK4 has been shown to play a role in promoting cancer progression in tumors." (PMID 40200093, 2025). "MAPK6/MAPK4 signaling regulates cell morphology, migration, endocytosis, and cell cycle progression, and its dysregulation is a known marker of cancer." (PMID 37746266, 2023). "We have previously demonstrated that overexpression of MAPK4 enhances cancer cell resistance to PI3K blockade." (PMID 37531320, 2023). "Yet, we can only partially rescue the MAPK4-mediated biology, such as promoting cancer cell/xenograft growth and their resistance to PI3K blockade." (PMID 37531320, 2023). "This supports an exciting therapeutic opportunity to use AKT and PDK1 inhibitors to treat MAPK4-high cancers, such as a large fraction of TNBC." (PMID 37531320, 2023). "They found that the gene that generates a protein called MAPK4 is significantly reduced in the cancer cells." (PMID 36797541, 2023). "In the gallbladder, overexpression of miR-136 suppressed cancer cell proliferation and enhanced apoptosis of cancer cells via inhibition of mitogen-activated protein kinase 4 (MAP2K4) gene expression." (PMID 33562573, 2021). "Mitogen Activated Protein Kinase-4 (MAPK-4) in different types of cancers is identified as an activating agent for AKT/mTOR signaling via alternative pathway." (PMID 33292283, 2020). "So far, little is known about the physiological function of MAPK4 and its involvement in diseases, including cancer." (PMID 32711558, 2020). "In contrast, how MAPK4 affects cancer cell response to the more stringent co-blockade of PI3K and PDK1 remains unknown." (PMID 37531320, 2023). "Besides enhancing resistance to PI3K blockade, MAPK4 also promotes cancer cell resistance to the more stringent PI3K and PDK1 co-blockade, a recently proposed therapeutic strategy." (PMID 37531320, 2023). "In addition, we depleted MIF in MAPK4-depleted BGC-823 cells in a coculture system of cancer cells and BMDMs." (PMID 36797541, 2023). "Although high concentration of AKT inhibitor treatment is very effective in inhibiting both the control and MAPK4-overexpressing cancer cell growth, the potential toxicity of AKT inhibitors at high concentrations is predicted to limit their therapeutic potential." (PMID 37531320, 2023). "Based on the concerted action of MAPK4-AKT and MAPK4-PDK1 axis in promoting cancer, we predict and confirm that co-targeting AKT and PDK1 effectively represses MAPK4-induced cancer cell growth, suggesting a potential therapeutic strategy to treat MAPK4-high cancers." (PMID 37531320, 2023). "Indeed, inhibiting MAPK4 sensitizes cancer cells to PI3K blockade." (PMID 37531320, 2023). "To examine whether MAPK4 plays a major role in regulating PDK1 protein stability, we first examined PDK1 protein stability in 7 TNBC cancer cell lines, including the MAPK4-low HCC1806, MDA-MB-468, HCC1395 cells, and the MAPK4-medium/high SUM159, MDA-MB-231, HCC1937, and HS578T cell lines." (PMID 37531320, 2023). "Besides, by enhancing PDK1 protein expression, MAPK4 may further enhance the canonical PI3K-PDK1-AKT pathway to promote cancer growth." (PMID 37531320, 2023). "Among the PPI proteins, six kinases were found to be associated with cancer pathways, including mTOR complex 1 (mTORC1), Janus kinase 1 (JAK1), Activin receptor type 1C (ACVR1C), Phosphorylase kinase catalytic subunit gamma 1 (PHKG1) and mitogen-activated protein kinase 4 (MAPK4)." (PMID 37355516, 2023). "If MAPK4 (TSS1500), HNRNPM, and PTGIR hypomethylation among smokers—what we observed—leads to greater protein expression, this could partially explain their increased risk for lung and heart diseases and several cancers." (PMID 35277542, 2022). "In numerous in vivo and in vitro studies, a variety of cancer-related mRNAs have been identified, including PTEN, ACTB, MAPK4, MKI67, c-MYC, and CD44." (PMID 40082414, 2025).
cancer (continued). "Since MAPK4 can PI3K/PDK1-independently activate AKT, we predicted and experimentally validated that MAPK4 renders cancer cell resistance to PI3K blockade." (PMID 37531320, 2023). "However, the role of MAPK4 in cancer metastasis remains unclear." (PMID 36797541, 2023). "This study shows that besides activating AKT, MAPK4 promotes PDK1 protein synthesis and thus also activates PDK1 substrates beyond AKT to promote cancer." (PMID 37531320, 2023). "By enhancing PDK1 protein expression, MAPK4 both activates PDK1 substrates beyond AKT and supports the PI3K-PDK1-AKT signaling cascade to regulate cancer cell biology." (PMID 37531320, 2023). "In contrast, our study demonstrated that the MAPK4-AKT signaling cascade can be activated by both insulin and EGF, two key factors regulating physiology and diseases, including cancers." (PMID 35017531, 2022). "The second subgraph, which contains the largest number of component nodes, has its 95 nodes anchored to the known cancer proteins CTNNB1, APC, PTEN, TP63, MAPK4, MET, RAC1, and ROS1." (PMID 24516372, 2014). "We have previously documented that MAPK4 can directly activate AKT independent of the canonical PI3K/PDK1 pathway to promote cancer growth." (PMID 37531320, 2023). "We recently reported that MAPK4 can promote cancer by noncanonically activating AKT independent of the PI3K/PDK1 signaling axis." (PMID 37531320, 2023). "We predict that the MAPK4-AKT axis may also sustain AKT phosphorylation/activation and provide MAPK4-high cancer cells resistance to combined PI3K and PDK1 inhibitors treatment." (PMID 37531320, 2023). "We recently reported that MAPK4 is a key oncogenic kinase promoting cancer via non-canonical activation of AKT/mTOR independent of PI3K/PDK116." (PMID 35017531, 2022). "Similarly, Mitogen-Activated Protein Kinase 4 (MAPK4) in 12 cancers, Serine/Threonine Kinase 32A (STK32A) and P21 (RAC1) Activated Kinase 3 (PAK3) in 10 cancers were found to be commonly downregulated." (PMID 33801837, 2021). "These include cancer hallmarks of various types: oncogenes (BCL2, BRAF), caspases (CASP6/7), transcription factors (E2F3), cell cycle genes (CDC42, CDK2, CDKN2A), cancer related kinases (JAK2/3, MAPK4/6/14) and DNA repair genes (BRCA1, PARP1 and RAD50)." (PMID 28059167, 2017). "Currently, there is no MAPK4 inhibitor to treat MAPK4-high cancers." (PMID 37531320, 2023). "Hence, the activation of the identified DEGs (MAPK4, MAPK15, and MAPK8IP3) might trigger the MAPK pathway and thereby influence drug resistance during cancer therapy." (PMID 37415453, 2023). "MAPK4 expression correlates negatively with infiltration by CD8+ T cells, plasmacytoid DC cells and T helper cells and correlates positively with the expression of inhibitory immune checkpoint proteins, which have been recognized as immunotherapy targets in cancer." (PMID 36999945, 2023). "Since our newly identified MAPK4-PDK1 axis can work with the MAPK4-AKT axis to promote cancer growth, we examined whether co-targeting PDK1 and AKT using PDK1 inhibitor GSK2334470 and AKT inhibitor MK2206 will be a valid approach to block MAPK4 tumor-promoting activities." (PMID 37531320, 2023).
infection (7 papers, 2014 to 2025). The state of being infected such as from the introduction of a foreign agent such as serum, vaccine, antigenic substance or organism. "The infection rate of C. parvum was significantly reduced in MAPK4-deficient host cells, which coincided with an increase in parasite-induced apoptosis, and a reduction in parasite invasion and asexual reproduction." (PMID 36658270, 2023). "In addition to its anti-apoptotic role, MAPK4 was also implicated in facilitating parasite invasion and asexual reproduction, indicating a broader role in the infection process." (PMID 40689036, 2025). "First, we assessed whether host MAPK4 deficiency influences the very first step of parasite infection; attachment." (PMID 36658270, 2023). "Four genes were annotated as mitogen-activated protein kinase 4/5 (Capana02g001328, Capana03g003283, Capana03g003841, Capana06g000135); they were downregulated in the resistant genotype and upregulated in the susceptible genotype after infection with PMMoV." (PMID 37152997, 2023). "To assess whether MAPK4 has a role in parasite invasion, we examined the effect of host MAPK4 deficiency on the invasion stage of C. parvum at 3 h post-infection." (PMID 36658270, 2023). "The infection rate was significantly decreased in MAPK4-KO HCT-8 cells by 20%, suggesting that host MAPK4 has an effect on the invasion of C. parvum." (PMID 36658270, 2023). "The exogenous overexpression of MAPK4 rescued the infection rate to 95% of that of WT cells, compared with mock-transfected MAPK4-KO HCT-8 cells at 65%." (PMID 36658270, 2023). "The observed reduction in infection rate suggests that host MAPK4 is an important host factor utilized by C. parvum to establish infection." (PMID 36658270, 2023). "Accordingly, we investigated the effect of host MAPK4 on the reproduction of C. parvum at 24 h post-infection, by counting the number of C. parvum in each phase of merogony in host cells." (PMID 36658270, 2023). "QRT-PCR analysis of C. parvum infection was also performed to ensure the phenomena, demonstrating the similar result of almost half the infection rates of MAPK4-KO cells over those of WT HCT-8 cells." (PMID 36658270, 2023). "WRKY33 forms a complex with MAP KINASE SUBSTRATE1 (MKS1), a substrate of MAPK4, and upon pathogen infection or elicitor treatment, activated MAPK4 phosphorylates MKS1 and releases WRKY33 from the complex." (PMID 34618142, 2021). "During infection, the expression of MAPK4 was decreased in transgenic plants while increased in WT plants, WRKY28 showed decrease in both transgenic and WT plants, while WRKY75 and WRKY33 showed increase in both transgenic and WT plants." (PMID 32455973, 2020). "Indeed, knocking out MAPK4 from HCT-8 colon adenocarcinoma cells significantly reduced infection, correlating with increased caspase-dependent apoptotic cell death induced by the parasite." (PMID 40689036, 2025). "The infection rate decreased by 45% as a result of MAPK4 knock out." (PMID 36658270, 2023). "We investigated the effect of MAPK4 on each of these stages of infection." (PMID 36658270, 2023). "The viability of processed sporozoites were analyzed by immunofluorescence assay with un-fixed WT and MAPK4-KO HCT-8 cells, ensuring the parasite development in host cells and the reduction of infection rate in MAPK4-KO cells after processed sporozoite infection." (PMID 36658270, 2023). "There was no change in viability of MAPK4-KO HCT-8 cells in the absence of C. parvum, whereas infected MAPK4-KO HCT-8 cells showed a 2.3-fold higher rate of cell death compared with infected WT HCT-8 cells at 24 h post-infection." (PMID 36658270, 2023). "MAPK4 could not be detected in soybean following infection with either virus, which is in line with a previous finding that the separate application of SA or flagellin failed to induce MAPK4 in soybean but did induce MAPK6." (PMID 37099452, 2023).
inflammation (1 paper, 2020). Aberrant reaction of the microcirculation characterized by movement of fluid and leukocytes from the blood into extravascular tissues. "Therefore, our current data revealed an unknown role of MAPK4, a member of atypical MAPKs, in the pathology of ALI, which might provide a light on the role of atypical MAPKs in inflammation related diseases." (PMID 33088477, 2020).
neurodevelopmental disorder (1 paper, 2023). A behavioral and cognitive disorder with onset during the developmental period that involves impaired or aberrant development of intellectual, motor, or social functions. "Here, we applied integrated genomic approaches for interrogating blood samples of two unrelated individuals with neurodevelopmental disorders and identified a novel neuro-pathogenic role for the Mitogen-Activated Protein Kinase 4 gene (MAP4K4)." (PMID 36469137, 2023).
MAPK4 also shares sentences with these, for which no sentence is quoted: colon cancer (5 papers); lung adenocarcinoma (4); bladder cancer (3); non-small cell lung carcinoma (2); adenocarcinoma (1); AIDS (1); Alzheimer disease (1); Arthritis (1); astrocytoma (1); cardiomyopathy (1); cervical tumors (1); diffuse large B-cell lymphoma (1); heart diseases (1); kidney cancer (1); left ventricular hypertrophy (1); liver inflammation (1); mastitis (1); oligoastrocytoma (1); oral squamous cell carcinoma (1); osteoporosis (1); pancreatic adenocarcinoma (1); rectal cancer (1); rheumatoid arthritis (1); skin cancer (1); Stroke (1); tongue cancer (1).